IDO1 (indoleamine 2,3-dioxygenase 1)
Diseases named in the same sentence as IDO1 in open-access papers (continued):
Sharing a sentence is not in itself a finding about the gene and the disease.
cancer (continued). "Increased insights in how the link between IDO1 and macrophages affects cancer immune escape and disease outcome may open new avenues for developing immune-based therapies." (PMID 35963900, 2023). "Moreover, our results suggest that surgery alters the IDO1-mediated immune status and that it induces significant changes in the IDO1-mediated immune activity level of cancer patients." (PMID 35963900, 2023). "Interestingly, many studies have shown that IDO1 is highly expressed in various types of human cancers." (PMID 37903782, 2023). "Notably, multiple lines of evidence link IDO1 expression with poor prognosis in patients with cancers." (PMID 37903782, 2023). "Blockade of the IDO1 pathway is an emerging modality of cancer immunotherapy." (PMID 38201582, 2023). "Indoleamine-2,3-dioxygenase 1 (IDO1), which is a cytosolic enzyme catalyzing the rate-limiting step of tryptophan (Trp) catabolism to kynurenine (Kyn), has been found to be a key factor in defining cancer immunogenicity." (PMID 36879122, 2023). "However, IDO1 is overexpressed in several cancer types and is prognostic for poor disease-free survival and overall survival." (PMID 37876966, 2023). "The results for IDO-1 were actually consistent in both types of cancers." (PMID 37181043, 2023). "Consequently, in 2017, IDO1 inhibitor was then praised as the next hot research spot for cancer immunotherapy by the American Society of Clinical Oncology." (PMID 36765782, 2023). "IDO-1 or CXCR-2 have previously been reported to inhibit cancer cell apoptosis." (PMID 37626777, 2023). "Furthermore, similar to TDO2, a high level of IDO1 transcription in cancer cells is sustained through an AhR-IL6-STAT3-driven positive feedback mechanism." (PMID 37999261, 2023). "The complexity of the TRP-depletion versus metabolite generation remains a puzzle of cellular biochemistry with a key practical implication: IDO1 inhibitors have thus far been unsuccessful in cancer therapy, despite IDO1 being one of the most rational and tractable pathways to target." (PMID 35245456, 2022). "Hence, amino acid-degrading enzymes that are substantially increased in cancer are of particular interest, i.e., indoleamine 2,3-dioxygenase 1 (IDO)-degrading l-tryptophan and arginases hydrolysing l-arginine." (PMID 36010962, 2022). "We have previously shown that IDO1 inhibition increased migration of PMNCs towards cancer cells." (PMID 35359980, 2022). "Cancer cells depend on IDO1 for exerting immunosuppressive effects." (PMID 36686754, 2022). "The discrepancy may be due to the cancer microenvironment and play a part in the low therapeutic efficacies of IDO1 inhibitors noted in previous clinical trials." (PMID 36233312, 2022). "The KP enzymes most studied in cancer are IDO1, TDO2 and IDO2." (PMID 36286592, 2022). "INCB024360 has a significant IDO1 inhibitor with desirable clinical outcomes in cancer patients." (PMID 35918736, 2022). "IDO1/TDO2 play important roles in cancer cell motility and their immune escape by catalyzing the initial and rate-limiting step of the tryptophan/kynurenine pathway, with its intermediates and end metabolites interfering with natural killer T cell interferon production." (PMID 35406118, 2022). "IDO1 therefore controls a multi-pronged protection pathway from ferroptotic cell death, underscoring the need to re-evaluate the use of IDO1 inhibitors in cancer." (PMID 35245456, 2022). "Because IDO inhibitors do not block IL4I1, these findings may explain the failure of a phase III clinical trial combining immune checkpoint blockade with IDO1 inhibition for cancer treatment." (PMID 36269001, 2022). "Tyk2 blocks induction of the IFNγ-regulated immune checkpoint Ido1 in Paneth-like cancer cells by an unknown mechanism." (PMID 36185806, 2022). "Like IDO1, TDO has been linked to immune resistance, including in mouse models where, in the presence of TDO inhibition, immune sensitivity was restored in those injected with TDO-expressing cancers." (PMID 36031601, 2022).
cancer (continued). "The studies performed on NK cells in cancers showed that INF-γ can induce IDO1 mRNA expression in NK cells, and pharmacological inhibition of the enzyme may reduce cytotoxicity against cancer cells both in in vitro and in vivo conditions." (PMID 35682852, 2022). "The high expressions of Axl, Tim-4, CD31, IDO1, ICAM1, and PD-L1 were associated with the high ESTIMATE score and immune score, while the high expressions of Axl, Tim-4, and CD31 were associated with the high stromal score in many types of cancers." (PMID 36059952, 2022). "Several candidate IDO1 inhibitors, including indoximod, navoximod, epacadostat, and linrodostat, have entered the clinical research stage for cancer immunotherapy." (PMID 36408235, 2022). "Interestingly, there has been more focus in recent years on targeting IDO1 in the cancer cells than in immune cells." (PMID 35997090, 2022). "It was demonstrated that blockade of IDO1 activity in cancer cells could reduce β-catenin activation and inhibit cell proliferation." (PMID 35371054, 2022). "However, opposing effects of IDO1 in TAMs have been observed, where IDO1-expressing cancer cells drive TAMs to impair T cell response." (PMID 35681736, 2022). "IDO1 is a new and reliable prognostic indicator for several cancers." (PMID 36139584, 2022). "IDO1 is also expressed in other cancers but at much reduced levels." (PMID 36286592, 2022). "IDO1 is frequently overexpressed in cancer cells and stromal cells in the TME37." (PMID 36163134, 2022). "For example, programmed cell death 1 (PD-L1), cytotoxic T lymphocyte antigen 4 (CTLA4), and the indoleamine 2, 3-dioxygenase 1 (IDO1) have achieved impressive success in the treatment of different cancer types, especially the combined treatment of PD-L1 and CTLA4." (PMID 35778697, 2022). "Indoleamine 2,3-dioxygenase 1 (IDO1) may be a target for cancer immunotherapy because it is a standard endogenous mechanism of acquired peripheral immunity." (PMID 35909469, 2022). "However, several recent reports have shown the therapeutic benefit of targeting IDO1 in cancer cells as well." (PMID 35997090, 2022). "Further investigation demonstrated that IDO1 is highly expressed in multiple types of human cancer." (PMID 36505882, 2022). "Indoleamine 2,3 dioxygenase 1 (IDO1) is an attractive target for cancer immunotherapy." (PMID 36163134, 2022). "Targeting IDO1 represents an opportunity in cancer immunotherapy beyond ICB." (PMID 36163134, 2022). "It is unknown if the prolonged activation of AhR affects cancer progression, considering that its activation by IDO1 inhibitors may induce pro-carcinogenic effects and can be associated with poor prognosis." (PMID 36119020, 2022). "Consequently, great efforts have been made to explore IDO1 inhibitors as the promising therapeutic candidate for cancer therapy." (PMID 36034879, 2022). "Consequently, IDO1 inhibitors have attracted the attention of scientists as potential cancer therapeutic drugs." (PMID 36355488, 2022). "Moreover, USP14 directly deubiquitinates and stabilizes IDO1 to protect it against ubiquitination and proteosome-mediated degradation in cancer cells." (PMID 36163134, 2022). "Therefore, IDO1 has obtained great attention as a therapeutic target with great potential in cancer immunotherapy in past decades." (PMID 35563059, 2022). "In addition, many cells belonging to the TME—fibroblasts, macrophages, MDSCs, and dendritic cells, including endothelial cells—are coerced by cancer cells to express IDO1, collectively supporting the immune escape." (PMID 35371054, 2022). "In recent years, numerous studies have been published related to IDO1 in cancer patients." (PMID 36212460, 2022). "The study showed that a high expression of IDO1 was associated with a poor OS and DFS in cancers." (PMID 36212460, 2022). "In addition, the activity of IDO1 has been reported to directly stimulate cancer growth and proliferation by the production of kynurenine and the activation of β-catenin signaling." (PMID 35572960, 2022).
cancer (continued). "IDO1 inhibitors were tested in several clinical trials for cancer immunotherapy." (PMID 36275666, 2022). "A pharmacologically optimized human kynureninase is currently moving toward clinical development for the treatment of cancers where Trp-Kyn-AhR pathway play a significant immunosuppressive role through Kyn production, and those independently of both IDO1 and TDO2 overexpression." (PMID 35173722, 2022). "Hence, interfering with the IDO1 pathway targeting cancer has become one of the focused areas in cancer immunotherapy research in recent years." (PMID 35681736, 2022). "Thus, intensive efforts should be made to investigate the efficient IDO1 inhibitors for cancer treatment." (PMID 35563059, 2022). "Furthermore, like TDO2, a high IDO1 transcription level is sustained in cancer cells by an AhR-IL6-STAT3-driven positive feedback mechanism." (PMID 35681770, 2022). "In a vitro experiment, IFN-γ was observed to promote autophagy in cervical cancer cells and enhance macrophages phagocytize autophagy-active cancer cells, the mechanism of which may be related to the overexpression of IDO1 and the accumulation of Kyn." (PMID 35681736, 2022). "IDO1 is a promising cancer therapeutic target that over expressed in many human cancers." (PMID 36034879, 2022). "Similarly, dihydrotanshinone I, which was isolated from the traditional Chinese medicine Radix Salviae Miltiorrhizae, is cytotoxic against many types of cancer cells and inhibits IDO1 with an IC50 of 2.8 μM." (PMID 36408235, 2022). "The recent failures of small-molecule IDO1 inhibitors, e.g., epacadostat, in Phase III clinical trials, highlight the significant challenges associated with translating the biology of Kyn pathway into effective cancer therapies." (PMID 35780226, 2022). "Therefore, given this functional circuitry between AhR and IDO1 and their functional relevance to cancer, our studies provide a novel insight into the anticancer efficacy of carbidopa." (PMID 35997090, 2022). "Therefore, this study provides valuable insights into the screen of more potent IDO1 inhibitors for cancer immunotherapy." (PMID 35563059, 2022). "In fact, IDO1 induces a novel tryptophan transporter expression in mouse and human cancer cells." (PMID 36119020, 2022). "Our recent drug screen and functional assay identified HSP90 as a universal control of the protein stability of nuclear transcription factor STAT1 in a variety of different cancer cells, thereby promoting subsequent gene expression of immune checkpoint molecules (IDO1 and PD-L1)." (PMID 35479647, 2022). "Furthermore, indoximod (1-Methyl-D-Tryptophan, 1-D-MT), a tryptophan analog, is a successful case for cancer treatment in clinical II stage targeting IDO1." (PMID 35563059, 2022). "It was reported that IDO1 was an immune checkpoint which could be potentially exploited to improve treatment outcomes in various cancers." (PMID 36212460, 2022). "In particular, IDO1 inhibitors have been aggressively explored as anti-cancer immunotherapies." (PMID 33831358, 2021). "Besides, several peptide vaccines targeting IDO1 have also entered the clinical assessment for examining the efficacy and safety and show promise for cancer therapy." (PMID 33883013, 2021). "As cancer cells display increased energy requirements, overexpression of IDO1 and KYNU may arise from the need of an additional source of energy NAD+." (PMID 33499346, 2021). "And further understanding of the immunobiological properties of IDO1, individual IDO1 expression levels, the optimal drugs targeting IDO1, and combination therapy strategies would lead to favorable treatment for patients with malignant tumors." (PMID 35003126, 2021). "Furthermore, the “proteolysis targeting chimera” (PROTAC) technology has also been successfully used in the development of IDO1 degraders, providing novel therapeutics for cancers." (PMID 33883013, 2021). "IDO1 is interferon-induced and has been shown to mediate powerful immunosuppression in cancer." (PMID 34778035, 2021).
cancer (continued). "However, IDO1 was also reported to be related to poor prognosis in some cancer and used as a checkpoint by tumors to escape immune surveillance." (PMID 34322485, 2021). "Since, a treatment can be quite effective in a specific subset without being effective in the whole cancer type, it is important to identify the subsets of cancers that may benefit from IDO-1 inhibitors." (PMID 34367262, 2021). "Also, 4,6-disubstituted indazole derivatives demonstrated the potential utility as IDO1 inhibitors in cancer treatment." (PMID 34201791, 2021). "Higher l-Kyn secretion suggests more active IDO1 enzyme in the cancer-derived cells." (PMID 33922995, 2021). "We further explored the correlation between YTHDC2 and eight immune checkpoint‐related genes and found that YTHDC2 was significantly associated with the expression of SIGLEC15, IDO1, CD274, HAVCR2, PDCD1, CTLA4, LAG3 or PDCD1LG2 in almost all types of cancers except for CESC and TGCT." (PMID 34312987, 2021). "Furthermore, a recent meta-analysis of 2706 patients from 24 articles found that high IDO1 expression is correlated with poor clinical outcomes in all cancers." (PMID 33557876, 2021). "Indoleamine-2,3-dioxygenase 1 (IDO1), a tryptophan (Trp)-catabolizing enzyme producing metabolites such as kynurenine (Kyn), is expressed by myeloid-derived suppressor cells (MDSCs) and associated with cancer immune escape." (PMID 33920868, 2021). "In a study profiling Trp metabolism in 928 cancer cell lines, Kyn secretion in the cancer cell media could be attributed to both IDO1 and TDO expression." (PMID 34557196, 2021). "The pan-cancer expression profile of IDO1 was analyzed using rank sum test." (PMID 34778035, 2021). "Thus, the pharmacological modulation of IDO1 and other enzymes that target amino acids have been included in cancer therapy strategies." (PMID 33747948, 2021). "Indoleamine-2,3-dioxygenase (IDO1) is a key enzyme to degrade amino acid tryptophan through the kynurenine pathway, which can regulate macrophages and inhibit the immune function of T cells in a variety of diseases and cancers." (PMID 34717710, 2021). "Finally, targeting the enzyme IDO1 seems a very promising strategy in the three cancer types studied for immunosuppression impairing, but most probably such treatment will need to be combined with other chemotherapies currently applied in each cancer type." (PMID 34588983, 2021). "Cancer suppression gene Bin1 could downregulate the expression of IDO1 via STAT1 and NF-κB dependent pathway." (PMID 33883013, 2021). "Therefore, the combination of IDO1 inhibitor with these therapies to defeat cancer has been paid high attention." (PMID 33557876, 2021). "Overall, these results shed increased light on IDO function, and suggest that IDO1 could have an important role beyond immune regulation, with the potential to influence one-carbon metabolism in cancer and stromal cells." (PMID 33831358, 2021). "LINC02672 was significantly correlated with the expression of IDO1, NRP1 and TNFSF4 in pan‐cancers, and it was significantly associated with the abundance of CD56 bright natural killer cells, mast cells, and immature dendritic cells in pan‐cancers." (PMID 33797188, 2021). "We next assessed whether IDO1 expression in the MLNs is a predictor of the cancer-immune set point in the immunoediting process." (PMID 34148865, 2021). "Many researchers have suggested that IDO2 could be an effective therapeutic target to treat inflammatory autoimmunity, while IDO1 has recently been under intense research focused on cancer immunotherapy." (PMID 34681715, 2021). "Therefore, there is an unmet need to develop and validate a relatively simple but accurate protocol for IDO1 enzyme activity estimation in cellular models of cancer biology." (PMID 33541164, 2021).
cancer (continued). "Although, preclinical studies found that targeting TDO significantly decreased the incidence of cancer progression and restored anticancer immunity, inhibition of IDO1 may enhance TDO expression and activity." (PMID 34201791, 2021). "Interestingly, IDO1 has been widely demonstrated to possess immunosuppressive functions, which are established to correlate with poor survival in various cancer patients." (PMID 33806305, 2021). "Elevated IDO1 expression in cancers has been correlated with single-agent ICI therapy resistance." (PMID 34069452, 2021). "The pan-cancer analysis identified that IDO1 was highly expressed in most cancers." (PMID 34778035, 2021). "Critically, understanding why IDO1 inhibitors failed in clinical trials may aid the future development of IDO-based cancer treatment." (PMID 34539663, 2021). "Moreover, we found IDO1 inhibitor (Epacadostat) can increase the expression of IDO1 and PD-L1 in some cancer cell lines." (PMID 34175886, 2021). "IDO1 is overexpressed in the vast majority of malignant tumors." (PMID 34943606, 2021). "IDO1 increased expression is reflected by the relative concentration of Kyn compared to Trp; hence, the Kyn/Trp ratio can be used as a prognostic clinicopathological marker to monitor cancer invasiveness and progression." (PMID 33922388, 2021). "High IDO1 expression correlates with poor prognosis in many types of cancer." (PMID 34943606, 2021). "Finally, IDO1 and the cytotoxic molecules including GZMA and PRF1 showed a positively stronger association with GMFG in most cancer types." (PMID 33863293, 2021). "On the other hand, pro-dormancy therapy through IDO1 activation may serve as an alternative strategy for cancer treatment, yet it requires additional investigation in the future." (PMID 34539663, 2021). "In conclusion, we have demonstrated a quantitative imaging method capable of specifically detecting dynamic IDO1 expression and monitoring the cancer-immune set point without the limitations associated with biopsy." (PMID 34148865, 2021). "In addition, IDO-1 is involved in cancer vascularization, metastasis and cancer progression, thus envisaging a target for potential immunotherapies." (PMID 33920505, 2021). "Most of them are IDO1 inhibitors developed for cancer therapy." (PMID 34201791, 2021). "A mechanism to escape the immunosurveillance could be played by indoleamine 2,3-dioxygenase 1 (IDO-1) that has been described in several human cancers." (PMID 33671892, 2021). "We, therefore, suggest that the combination of anti-IDO1 and anti-PD-L1 treatments might improve the efficacy of therapy against cancers that tend to evade single immunosuppressive treatment." (PMID 34373448, 2021). "Similarly, increased IDO1 activity is detected in LC patients, who initially respond to immune checkpoint inhibitors (ICIs) and later exhibit cancer progression, leading to a worse prognosis." (PMID 34422661, 2021). "Targeting IDO1 represents a therapeutic opportunity in cancer immunotherapy and might be an effective strategy for targeting ADPKD as well." (PMID 33758231, 2021). "In addition, the “proteolysis targeting chimera” (PROTAC) technique has also been employed to design PROTAC-based IDO1 degraders, which show promise for cancer immunotherapy." (PMID 33883013, 2021). "Hence, the usefulness of IDO1 inhibition as a strategy to enhance anti-PD-1 therapy activity in cancer yet to be clarified." (PMID 33747948, 2021). "During the IDO1-dependent metabolism of tryptophan through the kynurenine pathway, a number of metabolites are formed that are known to have potentially important roles in cancer metabolism." (PMID 33831358, 2021). "Additionally, in analysis of IDO1 expression based on cancer stage, we observed an increase in IDO1 at stages 1 to 3, with stage-dependent elevation mainly in the early to early-intermediate stages (stage 1 to 2)." (PMID 34769098, 2021).